DPP4 (dipeptidyl peptidase 4)
Diseases named in the same sentence as DPP4 in open-access papers (continued):
Sharing a sentence is not in itself a finding about the gene and the disease.
diabetes (continued). "New drugs for treatment of type 2 diabetes mellitus (T2DM) have proliferated over the past 15 years, with the introduction of glucagon‐like peptide 1 (GLP‐1) receptor agonists, dipeptidyl peptidase‐4 (DPP‐4) inhibitors and sodium‐glucose transport protein 2 (SGLT‐2 inhibitors)." (PMID 34277970, 2021). "In the current study, we here determined active GIP, GLP-1, and glucagon levels in type 2 diabetes mellitus (T2DM) subjects with or without DPP-4 inhibitor treatment to characterize the cell-based, receptor-mediated bioassays in comparison to immunoassays." (PMID 32390941, 2020). "DPP4 cleavage of the incretin peptides, glucagon-like peptide-1 (GLP-1) and gastric inhibitory polypeptide (GIP), have led to the development of DPP4 selective inhibitors as a successful type 2 diabetes mellitus (T2DM) therapy." (PMID 33218025, 2020). "Pre-clinical studies suggested potential cardiovascular benefits of dipeptidyl peptidase-4 inhibitors (DPP4i), however, clinical trials showed neither beneficial nor detrimental effects in patients with type 2 diabetes mellitus (T2DM)." (PMID 32168854, 2020). "Furthermore, AE was reported to improve islet structure in diabetes by PPAR-dependent mechanism, and active subfractions of AE substantially attenuated free fatty acid-induced β cell apoptosis through inhibiting dipeptidyl peptidase-4." (PMID 32467714, 2020). "However, the DPP4 activity was lower in plasma from patients with AAA compared with control subjects, independently of diabetes and medications but with indications of increased activity with smoking." (PMID 31971988, 2020). "Second, dipeptidyl peptidase-4 (DPP4) enzyme, a common pharmacological target for type 2 diabetes, was also a functional coronavirus receptor, which might be another potential mechanism that explains the link between COVID-19 and DM." (PMID 33584268, 2020). "Although currently available DPP4 inhibitors have good safety and tolerability, and most patients have only mild adverse reactions, there is interest in dietary therapies for diabetes that have relatively low efficacy but no adverse reactions." (PMID 32104696, 2020). "Current knowledge did not all support the beneficial effects of DPP4 inhibitors on patients with diabetes and COVID-19." (PMID 33584268, 2020). "In conclusion, long-term use of DPP-4 inhibitors in elderly diabetic patients with type 2 diabetes mellitus can effectively reduce HbA1C without weight gain, and has good safety of liver and kidney." (PMID 32368255, 2020). "Second, possible crosstalk between diabetes and COVID-19 might be involved with ACE2 and dipeptidyl peptidase-4, two important human proteins in the biological pathways of both diseases." (PMID 33472167, 2020). "In the Cardiovascular and Renal Microvascular Outcome Study with Linagliptin in Patients with Type 2 Diabetes Mellitus (CARMELINA study), the DPP4 inhibitor linagliptin retarded the albuminuria progression in patients with type 2 diabetes and high cardiovascular risk." (PMID 32340263, 2020). "Actually, drugs that target podocytes or vasculature, such as SGLT2 inhibitors and DPP-4 inhibitors, as well as drugs that can modulate HIF activity, may lead to next-generation therapeutics that can efficiently mitigate diabetes complications in the kidney." (PMID 33519447, 2020). "Altogether, these results indicate a direct association between DPP4 activity and insulin resistance, which is consistent with two studies that found positive associations between DPP4 activity and HOMA-IR in Chinese populations without diabetes." (PMID 30886868, 2019). "As the need for medical care in patients with HF and diabetes increases and the standard treatments are lacking, DPP-4 inhibitors and GLP-1 RAs, both anti-diabetic drugs, have shown beneficial effects in improving exercise tolerance in HF patients." (PMID 31870322, 2019).
diabetes (continued). "This study assessed the association between dipeptidyl peptidase-4 inhibitors (DPP-4i) and the risk of cardiovascular events in patients with type 2 diabetes mellitus with or without chronic kidney disease (CKD)." (PMID 31112536, 2019). "Positive effects were also reported in the absence of diabetes, although with gliptins with relatively low DPP4 selectivity." (PMID 30774748, 2019). "Three cardiovascular outcome trials with the DPP-4 inhibitors alogliptin, saxagliptin and sitagliptin were published and demonstrated cardiovascular safety of those molecules as compared to usual diabetes care without DPP-4 inhibitors." (PMID 29773079, 2018). "In the setting of diabetes, SDF-1α may be rapidly degraded by local and circulating DPP-4 activity which may limit mobilization and attachment of stem cells to injured tissue." (PMID 29669555, 2018). "Differences in the efficacy of DPP-4 inhibitors have been observed between Asian and non-Asian patients with diabetes, presumably reflecting differences in the diabetic phenotype." (PMID 29435909, 2018). "Although additional studies are needed to clarify the mechanisms of DPP-4 shedding in the context of diabetes, our results indicate that this DPP-4i could exert positive actions beyond the direct inhibition of the DPP-4 enzyme." (PMID 29507662, 2018). "In addition, GLP-1 is the most important substrate of DPP-4 and can mediate the multiple actions of DPP-4 inhibition in cardiovascular disease and diabetes." (PMID 29607314, 2018). "Although oral DPP-4 inhibitors are used to treat diabetes, intraperitoneal injection of vildagliptin did not lead to significant hypoglycemia in this study (data not shown)." (PMID 29037205, 2017). "DPP-4is is a new class of anti-diabetes which can prevent the rapid degradation of glucose-dependent insulinotropic polypeptide (GIP) and glucagon-like peptide 1(GLP-1) through inhibition of DPP-4, thus enhancing insulin secretion." (PMID 29206832, 2017). "In the stratified analysis, the aHRs for DPP-4 inhibitors compared with glimepiride did not increase as diabetes duration and treatment duration increased." (PMID 28640111, 2017). "The aim of this study is to determine the pharmacokinetics (PK) and pharmacodynamics (PD) of a single 12.5- or 25-mg dose of alogliptin, a dipeptidyl peptidase-4 (DPP-4) inhibitor, in pediatric (children and adolescents) and adult subjects with type 2 diabetes mellitus (T2DM)." (PMID 27999883, 2017). "DPP-4 inhibitors did not increase cardiovascular risk compared with glimepiride regardless of CVD history and diabetes duration." (PMID 28640111, 2017). "Glucagon-like peptide 1 (GLP-1) improves endothelial function in diabetes, so therapeutic strategies for patients with T2DM are focused in increasing the incretin response, either by inhibiting dipeptidyl peptidase-4 (DPP-4) activity or by using degradation-resistant GLP-1 analogues." (PMID 27530507, 2017). "Our findings suggest that therapies that augment β cell function such as glucagon-like peptide-1 or dipeptidyl peptidase-4 inhibitors, but not sulfonylureas would be more effective in the management of diabetes among Japanese." (PMID 27830830, 2016). "The 52-week monotherapy with the dipeptidyl peptidase-4 inhibitor sitagliptin and the sulphonylurea glimepiride on early-phase insulin secretion in Japanese patients with type 2 diabetes mellitus (T2DM) is not known." (PMID 26925169, 2016). "In summary, targeting DPP4 may be a novel way of suppressing renal injury under the setting of inappropriate renal RAS activation such as obesity and diabetes." (PMID 27213360, 2016). "In the present study, we assessed the effects of DPP-4 inhibitors on post-infarction sympathetic innervation in rats without diabetes." (PMID 26811539, 2016).
diabetes (continued). "Moreover, the mammalian kidney has high concentrations of DPP-4, and the expression of DPP-4 is increased in cultured human renal glomerular epithelial cells during inflammation and in a rat model of type 2 diabetes mellitus." (PMID 26877767, 2016). "However, no studies have examined the effect of empagliflozin or the combination of DPP-4 inhibitors and SGLT2 inhibitors on the development of NASH in the presence of diabetes." (PMID 27462372, 2016). "Further longitudinal study is needed to clarify whether DPP-4 inhibitors and/or GLP-1-based therapies could prevent the development and progression of devastating complications of diabetes." (PMID 25582643, 2015). "We aimed to evaluate the efficacy and safety of the three dipeptidyl peptidase 4 (DPP-4) inhibitors (vildagliptin, sitagliptin, and linagliptin) as add-on therapy in Chinese patients with type 2 diabetes mellitus (T2DM)inadequately controlled on dual combination of insulin and metformin or acarbose." (PMID 26500706, 2015). "Recent studies indicate that commonly used drugs in diabetes, including ACE inhibitors, DPP4 inhibitors, GLP-1 agonists, insulin, metformin, statins, or thiazolidinediones, may increase the number of EPCs and improve EPC function." (PMID 26077117, 2015). "A more recent study that compared serum levels and plasma activity of the DPP4 among patients with T2DM and healthy subjects showed significant higher levels and activity of the DPP4 in those with diabetes than in controls, but only after excluding patients treated with metformin and/or glitazones." (PMID 26146634, 2015). "There have only been a few reports about use of dipeptidyl peptidase 4 (DPP-4) inhibitors in elderly patients with type 2 diabetes mellitus (T2DM), suggesting that the safety of these agents has not been sufficiently demonstrated." (PMID 26137940, 2015). "The data confirm that DPP4 inhibitors, currently used in clinics for the treatment of DMT2, may be effective also against skin complications that occur during diabetes." (PMID 26136686, 2015). "Considering the higher concentrations and activity of DPP4 in patients with diabetes when compared to nondiabetic subjects, it is possible that DPP4 constitutes a new link between diabetes and atherosclerosis." (PMID 26146634, 2015). "Animal models have demonstrated that DPP-4 inhibitors improve glucose intolerance in early-stage diabetes, but not in the late stage of the disease, suggesting that DPP-4 inhibitors are more effective in the presence of functional β-cells." (PMID 21443773, 2011). "The dipeptidyl peptidase-4 (DPP4) inhibitors are a novel class of antidiabetic drugs with a good safety profile and which are now being considered in some algorithms for the treatment of type 2 diabetes mellitus (T2DM)." (PMID 21159194, 2010). "In this point, treatment with GLP-1 mimetic agents, including DPP-4 inhibitors and GLP-1 analogs, may be a novel therapeutic strategy for patients with not only diabetes but also MetS and atherosclerosis-prone conditions." (PMID 20470376, 2010). "After adjusting for HbA1c, BMI, and diabetes duration, patients on insulin therapy (22.8 ± 1.5 ng/mL) showed significantly higher NOX2 levels compared to those on metformin alone (19.8 ± 0.9 ng/mL, p = 0.041) or DPP-4 inhibitors alone (18.9 ± 1.2 ng/mL, p = 0.028)." (PMID 41607455, 2026). "In addition, according to observational and experimental data, DPP4 inhibitors, sulfonylureas, and insulin, are unlikely to slow cognitive decline beyond the benefits of glycemic control in diabetes without dementia." (PMID 41420258, 2025). "In Japan, where over 70% of individuals with diabetes are aged 65 or older and often exhibit a non-obese phenotype with impaired insulin secretion, dipeptidyl peptidase-4 inhibitors remain a cornerstone therapy due to their ability to enhance insulin secretion without increasing hypoglycemia risk." (PMID 40607140, 2025).
diabetes (continued). "Notably, patients with diabetes with AD-related cognitive impairment using DPP-4 inhibitors exhibit a lesser amyloid burden and slower cognitive decline compared to patients without diabetes or patients with diabetes taking other glucose-lowering medications." (PMID 39904872, 2025). "Presently, it may be conjectured that DPP-4 inhibitors could be deemed an efficacious medication for patients battling diabetes without considerable complications." (PMID 40832578, 2025). "Post prandial C-peptide was non-significantly higher with DPP-4 inhibitors vs. placebo in the subgroup analysis according to diabetes duration: MD = 19.91 [−11.97, 51.79], p = 0.22 in diabetics < 1 year vs. MD = 279.89 [−7.78, 567.57], p = 0.06 for diabetics since 1 to 3 years ago." (PMID 41026724, 2025). "Additionally, elevated levels of dipeptidyl peptidase-4 (DPP-4) have been identified in individuals with FPLD, suggesting that DPP-4 inhibitors may be a relevant therapeutic option for managing diabetes in these patients." (PMID 40452043, 2025). "Independent of diabetes, it has been found that DPP-4 inhibitors reduce cardiac fibrosis." (PMID 40429343, 2025). "Additionally, DPP4 is a serine exopeptidase, and its inhibitors represent a novel therapeutic option for type 2 diabetes mellitus." (PMID 41357233, 2025). "Dipeptidyl peptidase-4 (DPP-4) is a serine aminopeptidase, commonly referred to as CD26, an enzyme that is necessary for regulating glucose metabolism and immune function, and is one of the validated targets for diabetes therapy due to its regulatory effect on incretin hormones." (PMID 38675143, 2024). "DPP4 inhibitors like APL and PVI are potential antidiabetic peptides for lowering glycemic indices, lowering the amount of glucagon, and maintaining insulin levels in type 2 diabetes mellitus, and their activities are indirectly facilitated by the continuous presence of GLP-1 incretin." (PMID 36982902, 2023). "Although studies on coronary perfusion with DPP4i are lacking, there are some clinical studies that suggest DPP4 inhibition may improve coronary flow reserve and myocardial perfusion reserve in patients with diabetes and CAD." (PMID 37300400, 2023). "This newly discovered regulatory mechanism may help to develop novel analgesics, since the currently available DPP4 inhibitors used for diabetes therapy do not pass the blood brain barrier." (PMID 36674439, 2023). "Previous studies have reported that dual drug combinations consisting of γ-aminobutyric acid (GABA) together with a dipeptidyl-peptidase-4 inhibitor (DPP-4i), also a DPP-4i with a proton pump inhibitor (PPI), could improve pancreatic β-cell function and ameliorate diabetes in diabetic mice." (PMID 36339443, 2022). "Several studies showed that cardiovascular health in patients with diabetes might significantly benefit from antihyperglycaemic medications, such as glucagon-like-peptide 1 (GLP1) agonists, dipeptidyl peptidase 4 (DPP4) inhibitors, and sodium-glucose cotransporter-2 inhibitors (SGLT2i)." (PMID 36589802, 2022). "DPP4 has been known to regulate glucose metabolism by inactivation of GIP; both GLP-1 and DPP4 inhibitors have been used for type 2 diabetes mellitus (DM) treatment." (PMID 35251476, 2022). "In addition, the retinal pigment epithelium of subjects with diabetes present higher DPP-4 concentrations than non-diabetic controls matched by age." (PMID 35203674, 2022). "We found that diabetes-induced M1 cytokine expression in adipose tissue, promoted M1 cytokine expression and JNK and NF-κβ activation in liver, and enhanced plasma DPP4 activity that may subsequently promote insulin resistance and glucose intolerance in diabetic mice." (PMID 35883204, 2022). "In addition, the injection of nondiabetic plasma-treated SVFs not only repressed the expression of the diabetes-induced ICAM, FMO3, IL-6, IL-1β, iNOS, TNF-α, and DPP4 expression, but also suppressed the phosphorylation of JNK and NF-κB in the liver of diabetic mice." (PMID 35883204, 2022).
diabetes (continued). "On the other hand, different diabetes drugs, such as metformin, thiazolidinediones (TZD), glucagon-like peptide-1 receptor (GLP-1R) agonists, dipeptidyl peptidase-4 (DPP-4) inhibitors, and sodium-glucose cotransporter (SGLT2) inhibitors, could be used as treatment strategies for PCOS." (PMID 36588716, 2022). "Sodium-glucose co-transporter 2 (SGLT2) inhibitors, glucagon-like peptide-1 receptor (GLP-1R) agonists, and dipeptidyl peptidase 4 (DPP-4) inhibitors showed significant benefit on cardiovascular outcomes in both patients with and without type 2 diabetes mellitus (DM)." (PMID 33843015, 2022). "Finally, some of the newest drugs used to treat diabetes (e.g., glucagon-like peptide-1 (GLP-1) receptor agonists and dipeptidyl peptidase-4 (DPP-4) inhibitors) may exert some promoting effects on the development of NETs." (PMID 35681699, 2022). "Collectively, our findings reveal that the suppression of DPP4 expression in adipose tissue and DPP4 activity in plasma with nondiabetic plasma-treated SVFs may ultimately attenuate glucose intolerance and insulin resistance in diabetes." (PMID 35883204, 2022). "In patients developing overt diabetes, most common flow-charts suggest metformin as a first-line therapy and, whether abnormal glucose profile persists, a GLP-1 receptor agonist (GLP1-RA) or a dipeptidyl-peptidase-4 inhibitor (DPP4-i)." (PMID 35744057, 2022). "The aim of this study was thus to assess the prognostic impact of DPP4i in patients with both diabetes and coronary artery disease (CAD) who underwent percutaneous coronary intervention (PCI) through the insulin-like growth factor-1 (IGF-1) axis, a substrate of DPP4." (PMID 35332212, 2022). "The protocol for a three-way crossover study including a DPP4 inhibitor, thiazolidinedione and a SGLT2 inhibitor has been described, which will provide further information on stratification of glucose response to three diabetes medications by routine clinical features ascertained at baseline." (PMID 36699039, 2022). "Alternatively, the role of DPP-4 in diabetes is not restricted to its GLP-1 degrading properties." (PMID 34531738, 2021). "The use of DPP-4 inhibitors as anti-inflammatory agents in patients without diabetes may also lead to different clinical outcomes than those presented in this manuscript." (PMID 35002970, 2021). "In the present cross-sectional study, we investigated whether the plasma nesfatin-1 and DPP4 is associated with the prevalence and severity of coronary artery disease (CAD) with and without diabetes mellitus (DM)." (PMID 34389003, 2021). "Additional analyses comparing users of DPP-4 inhibitors with subgroups of non-users (subgroup 1: users of metformin and sulphonylurea; subgroup 2: users of any insulin combination), allowing to correct for diabetes severity, did not yield different results." (PMID 34222054, 2021). "The inhibition of M1 expression in the adipose tissue represses JNK activation, plasma DPP4 activity and CCL2 levels, as well as liver inflammatory cytokines expression that may ultimately attenuate insulin resistance and glucose intolerance in diabetes." (PMID 34043673, 2021). "Sodium-glucose cotransporter 2 (SGLT2) and dipeptidyl peptidase-4 (DPP-4) inhibitors are glucose-lowering drugs whose anti-inflammatory properties have recently become useful in tackling metabolic syndromes in chronic inflammatory diseases, including diabetes and obesity." (PMID 34124273, 2021). "Interestingly, ACE2 and DPP4 were connected irrespective of the pancreatic nature i.e., healthy, cancer and diabetes mellitus." (PMID 33796097, 2021). "Current investigation into the usage of established diabetes drugs in the management of PD is now under trial including sodium-glucose cotransporter 2 (SGLT2) inhibitors, glucagon-like peptide-1 receptor agonists (GLP-1RA), and dipeptidyl peptidase-4 (DPP-4) inhibitors." (PMID 34943038, 2021).